ACE (angiotensin I converting enzyme)
Diseases named in the same sentence as ACE in open-access papers (continued):
Sharing a sentence is not in itself a finding about the gene and the disease.
Hypertension (continued). "Regarding association studies of ACE I/D polymorphism with hypertension, only two studies were conducted on Egyptians and they associated the D allele with hypertension, mainly on noise exposure." (PMID 27777603, 2016). "Our objective was to study the association of ACE I/D polymorphism with obesity and certain related disorders, namely hypertension, insulin resistance and metabolic syndrome, in Egyptian females." (PMID 27777603, 2016). "ACE I/D polymorphism can serve as a marker for early diagnosis of hypertension if we have similar findings elsewhere." (PMID 26351579, 2015). "AGT, ACE, and AT1R genes have overall effects with susceptibility to hypertension, where the SNPs of ACE have a mainly hypertension-associated effect and show an interacting effect to SNPs of AGT and AT1R genes." (PMID 25961019, 2015). "Our results showed a strong association between the ACE I/D polymorphism and the development of hypertension." (PMID 26351579, 2015). "Inhibition of angiotensin-converting enzyme (ACE) is among one of the most effective treatments for hypertension and end-organ damage associated with diabetic nephropathy." (PMID 26536600, 2015). "This work was designed to investigate the effect of Soursop fruit parts (pericarp, pulp, and seed) extracts on key enzymes (α-amylase and α-glucosidase) linked with type-2 diabetes and [angiotensin-I converting enzyme (ACE)] hypertension." (PMID 26788368, 2015). "In OSAS patients complicated with hypertension, the significant associations of ACE gene I/D polymorphism with OSAS susceptibility were identified under three genetic models." (PMID 26486181, 2015). "Second objective was to investigate the association between ACE I/D polymorphism and hypertension risk." (PMID 26491214, 2015). "The risk of hypertension associated with ACE DD is modulated by obesity status and hence future genetic association studies should take obesity into account for the interpretation of data." (PMID 26491214, 2015). "More studies involving ACE I/D polymorphism with hypertension therapeutic responses are still needed to better monitor and provide individualized care for hypertensive patients." (PMID 26351579, 2015). "The 2- to 6-locus models suggest that those SNPs of the AGT and ACE genes were associated with hypertension." (PMID 25961019, 2015). "In 2- to 6-locus models of the SNP-SNP interaction, the SNPs of AGT and ACE genes were associated with hypertension (bootstrapping odds ratio [Boot-OR] = 1.972~3.785; 95%, confidence interval (CI) 1.26~6.21; P < 0.005)." (PMID 25961019, 2015). "Among them, SNP I/D of ACE has the main association effect to hypertension and it also displays n-order interaction effect to SNPs of AGT and AT1R genes although they do not have a mutual effect on each other." (PMID 25961019, 2015). "Only two genes were significantly associated with the hypertension and hypercholesterolemia (HH): ACE (OR: 9.20, P<0.0001) and PAI-1 (OR: 2.29, P = 0.007)." (PMID 25973747, 2015). "This study investigated the effects of aqueous extracts (1 : 100 w/v) of Soursop fruit part (pericarp, pulp, and seed) on key enzymes linked to type-2 diabetes (α-amylase and α-glucosidase) and hypertension [angiotensin-I converting enzyme (ACE)]." (PMID 26788368, 2015). "Our study also highlights obesity as an important modulator of ACE polymorphism, suggesting that future genetic association studies for hypertension should take obesity status into account when interpreting data." (PMID 26491214, 2015). "Hypolipidemic agents and ACE inhibitors have beneficial effects on hs-CRPbecause these drugs act on the control of lipid profile and hypertension, which areimportant risk factors to the development of atherosclerosis." (PMID 26647745, 2015). "Several studies have established that the renin-angiotensin system, including the ACE insertion/deletion genetic polymorphisms has been implicated in the pathogenesis of essential hypertension." (PMID 25973747, 2015).
Hypertension (continued). "The ACE I/D polymorphism has been extensively studied and points to an association with arterial hypertension." (PMID 25984491, 2014). "Variables which identified as significant in the univariate analysis (diabetes mellitus, hypertension, hyperlipidemia, current smoking, ACE D/D and I/D polymorphism) were included in the model." (PMID 25161389, 2014). "Several polymorphisms have been associated with higher prevalence of arterial hypertension; there are 2 polymorphisms in the Angiotensin Converting Enzyme (ACE) and Angiotensin Converting Enzyme 2 (ACE2) that lead to elevate circulating Ang II levels." (PMID 25232536, 2014). "Several studies have demonstrated the importance of ACE I/D polymorphisms in the pathogenesis of hypertension." (PMID 24523965, 2014). "In agreement with previous studies, ACE D/D gene polymorphism, diabetes mellitus and hypertension were found to be the independent predictive factors for RVO." (PMID 25161389, 2014). "In our study, the ACE D/D gene polymorphisms, diabetes mellitus, hypertension, hyperlipidemia, and smoking were found to be significantly higher in the RVO group compared to controls." (PMID 25161389, 2014). "AGT gene encoding angiotensinogen and ACE gene encoding angiotensin-converting enzyme were investigated most extensively and have been shown to be associated with hypertension." (PMID 25313554, 2014). "ACE expression in blood vessels is normally limited to endothelial cells; however, hypertension and atherosclerosis are associated with ACE expression on human endothelial cells, subendothelial neointimal cells, and SMCs." (PMID 25222748, 2014). "Alu insertion is well described in angiotensin converting enzyme (ACE) polymorphism, and its relation to hypertension, diabetes and metabolic syndrome." (PMID 24767306, 2014). "A local increase of angiotensin-converting enzyme (ACE) in the kidney was associated with the progress of tubulointerstitial renal injury by hypokalemia, hypertension, and angiotensin II infusion in rats." (PMID 25140450, 2014). "Inhibition of angiotensin -1- converting enzymes (ACE) activity is currently use in the management of hypertension which is the one of the complications associated with type-2-diabetes." (PMID 25598760, 2014). "Our study showed a lower OR 0.401 (95% CI 0.224–0.718; P < 0.01) compared to a recent meta-analysis in whole Chinese population which reports high association with ACE DD polymorphism with hypertension (OR = 1.27; 95% CI 1.17–1.46; P < 0.01)." (PMID 24860821, 2014). "A recent study from our group proposed an involvement of ACE insertion/deletion (I/D) polymorphisms in the mechanisms of fetal programming of hypertension." (PMID 25170764, 2014). "Meta-analyses in different studies also found that DD genotype of ACE I/D polymorphism and AA genotype of ACE G2350A polymorphism are associated with essential hypertension." (PMID 24860821, 2014). "In summary, the genotype distributions of the AGT M235T polymorphism influenced the risk of essential hypertension in south Indian women and ACE DD is a risk in south Indian male population." (PMID 24860821, 2014). "The antioxidant properties and effect of essential oil of black pepper (Piper guineense) seeds on α-amylase, α-glucosidase (key enzymes linked to type-2 diabetes), and angiotensin-I converting enzyme (ACE) (key enzyme linked to hypertension) were assessed." (PMID 24348547, 2013). "There are few reports on ACE mRNA expression level in blood and hypertension and less on the association of ACE mRNA expression level with hypertension in tissue." (PMID 24098401, 2013). "In summary, in Chinese elderly population, DD genotype and D allele in ACE gene were associated with hypertension and lipid levels." (PMID 24354906, 2013). "These two major QTLs of ACE activity and the moderate effect variant upstream of ACE promoter for young-onset hypertension were replicated by another independent association study with 842 subjects." (PMID 23469169, 2013).
Hypertension (continued). "On the other hand, rs1800764, the tag-SNP representing the LD block 2 of ACE, was the only SNP that was moderately but significantly associated with young-onset hypertension." (PMID 23469169, 2013). "And the association between the ACE gene polymorphism and the pathology of hypertension or diabetes has been paid more attention recently." (PMID 24354906, 2013). "The results suggest that single nucleotide polymorphisms and the “GGATG” haplotype of the ACE gene are associated with the development of hypertension and with increased ACE enzyme levels." (PMID 23741507, 2013). "Indicating that ACE gene deletion polymorphism was associated with the pathogenesis of hypertension in elderly." (PMID 24354906, 2013). "Overactivation of the RAS in diabetes, especially Ang II and ACE, leads to hypertension, fluid retention, and inflammation, causing renal and vascular end-stage disease in the long term." (PMID 23646149, 2013). "In the present study, we utilized the case - control study to analyze the relationship between the ACE gene polymorphism and elderly hypertension and diabetic hypertension." (PMID 24354906, 2013). "A tag-SNP, rs1800764 on LD block 2, upstream of and near the ACE promoter, was significantly associated with young-onset hypertension (p = 0.04)." (PMID 23469169, 2013). "Three major trials have addressed the use of ACE inhibitors for hypertension in patients with or at high risk of CHD." (PMID 23476746, 2013). "In conclusion, we have discovered a moderate effect variant upstream of ACE promoter for young-onset hypertension and two QTLs of ACE activity, one from exon 13 to intron 18 and the other from intron 20 to 3′UTR." (PMID 23469169, 2013). "Angiotensin-converting enzyme (ACE) inhibitor use was associated with a significantly lower risk of headache in patients with hypertension." (PMID 23773858, 2013). "The potential role of the I/D polymorphism and thus of differential ACE plasma activity and ACE mRNA expression in the development of hypertension is still a matter of controversy." (PMID 24098401, 2013). "We genotyped 31 single nucleotide polymorphisms (SNPs) of ACE from 1168 individuals from 305 young-onset (age ≤40) hypertension pedigrees, and found four linkage disequilibrium (LD) blocks." (PMID 23469169, 2013). "A number of research papers have reported a significant association between ACE I/D polymorphism and a series of diseases, including hypertension, type 2 diabetes, cardiovascular disease, kidney disease, cancer, and obesity." (PMID 23717661, 2013). "We performed logistic regression to assess associations of ACE I/D genotypes, ACE activity, and ACE mRNA expression levels with hypertension." (PMID 24098401, 2013). "Data strongly suggest that normotensive subjects from group 1 (65, 90, and 190 kDa ACE isoforms) deserve special attention when it comes to prevention since 90 kDa N-domain isoform is positively associated with hypertension." (PMID 22666552, 2012). "Statistical analysis showed a positive association between 90 kDa N-domain ACE isoform and presence of hypertension." (PMID 22666552, 2012). "In this context, functional polymorphisms of the ACE gene have been linked to depression, to antidepressant treatment response, to ACE serum concentrations, as well as to hypertension, myocardial infarction and CVD risk markers." (PMID 22808171, 2012). "eNO is now of interest in murine models of anaphylaxis, where chronic blockade of eNO increases expression of mRNA for renin, ACE, and AI receptors in the aorta, with the risk of hypertension." (PMID 23316249, 2012). "A reduction in the basal NO production was suggested, confirmed by NO urine analysis in subjects with the 90 kDa N-domain ACE isoform alone or associated with a family history of hypertension." (PMID 22666552, 2012). "In conclusion, traditional risk factors (hypertension, smoking and dyslipidemia) play an important role in the association between ACE genotypes and PAD." (PMID 22144991, 2012).
Hypertension (continued). "Recently we described the association of 90 kDa N-domain ACE with plasma inflammatory markers, endothelial function, and family history of hypertension." (PMID 22666552, 2012). "The second example relates to the ACE gene locus, which is a known risk locus for cardiovascular disease, hypertension and kidney failure." (PMID 23093944, 2012). "In this context, functional polymorphisms of the ACE gene have been linked to depression, hypertension and myocardial infarction." (PMID 22808171, 2012). "ACE D/D genotype was associated with hypertension (p = 0.004), peripheral vascular disease (p = 0.006), and previous myocardial infarction (p = 0.007)." (PMID 21955693, 2011). "The genetics of hypertension-associated treatment (GenHAT) study investigated the ACE insertion/deletion (ACE I/D) polymorphism in a large population of hypertensive patients with one or more cardiovascular risk factors." (PMID 22135769, 2011). "For example, thiazide diuretics cause hypokalaemia when used to treat hypertension, while this side effect can be prevented by angiotensin-converting enzyme (ACE) inhibitors when they are used concurrently." (PMID 22219721, 2011). "In humans, polymorphisms in the angiotensin-converting enzyme (ACE) gene modulate susceptibility to hypertension in sleep apnea, and increased RAS activity is associated with glomerular hyperfiltration, a precursor to kidney disease." (PMID 21559506, 2011). "The absence of the I allele of the angiotensin converting enzyme (ACE) gene has been associated with higher levels of circulating ACE, lower nitric oxide (NO) release and hypertension." (PMID 22136292, 2011). "By contrast, the associations of the ACE I/D polymorphism with hypertension and cardiovascular disease have been inconsistent." (PMID 23049672, 2011). "The ACE I/D polymorphism appears to influence ACE expression and blood pressure, with the D allele and DD genotype being associated with high blood pressure, while the II genotype and the I allele are associated with lower blood pressure." (PMID 21633717, 2011). "The number of studies carried out around the world suggested the genetic predisposition of the ACE I/D polymorphism with several diseases including coronary heart diseases, stroke, hypertension and diabetes mellitus." (PMID 28352369, 2010). "In conclusion, the present study carried out for the first time in our population clearly indicates the strong association of ACE I/D polymorphism with hypertension." (PMID 28352369, 2010). "Another study carried out in Bangladeshi population found a significant association of ACE I/D polymorphism with hypertension." (PMID 28352369, 2010). "The aim of the present work was to explore the effect of captopril, a known ACE inhibitor, on the cardiovascular inflammatory process associated with arterial hypertension." (PMID 20462420, 2010). "Only the presence of hypertension was significantly associated with the use of an ACE inhibitor (P=.009, odds ratio=2.7)." (PMID 19318756, 2009). "In a case-control study of hypertension in adolescents, a significant dominant effect of ACE D alleles on SBP was found in boys only." (PMID 19291311, 2009). "Renin angiotensin system (RAS) blockade by either ACE inhibitors or angiotensin II receptor blockers (ARBs) is associated with a reduced risk of AF in patients with hypertension or heart failure." (PMID 19471593, 2009). "The present study is the first report investigating the association of ACE I/D polymorphism with hypertension in a rural population of Haryana." (PMID 20009302, 2009). "Despite the recent findings, the current evidence indicates any effect of the ACE D allele on the risk of hypertension in adults is small to moderate at best." (PMID 19291311, 2009). "The present study is aimed to determine the association, if any, of ACE I/D polymorphism with essential hypertension in a rural population of Haryana, India." (PMID 20009302, 2009).
Hypertension (continued). "In population studies genetic variants of the RAS are associated with an increased risk of hypertension, notably the ACE insertion deletion (ACE I/D) and AT1R A/C polymorphisms." (PMID 17204161, 2007). "Still, association studies targeted to ACE polymorphisms are inconsistent about the role of ACE variants providing susceptibility to hypertension." (PMID 17645789, 2007). "The ACE gene rs4343 (2350 G/A) polymorphism was analyzed in Chinese patients with hypertension." (PMID 41595504, 2026). "Therefore, there is a need to design more selective ACE inhibitors that preferentially target either nACE or cACE for the treatment of inflammation, fibrosis, postmyocardial infarction and hypertension, which would be associated with fewer side effects." (PMID 40824896, 2026). "Based on these findings, it may be possible to identify high-risk individuals for hypertension using ACE gene SNPs and to prevent or delay the onset of hypertension by providing targeted lifestyle interventions from a younger age." (PMID 40370871, 2025). "Our results indicate that clinical factors, such as a higher body mass index, elevated triglycerides, suboptimal glycemic control, and female gender, are more predictive of hypertension development than genetic risk factors like ACE and AGTR1 gene polymorphisms." (PMID 40149592, 2025). "As overexpression of angiotensin-converting enzyme (ACE), which is a fundamental component in the renin-angiotensin-aldosterone system (RAAS) regulating blood pressure, is associated with vascular hypertension, inhibition of ACE is of great importance in respect to hypertension." (PMID 40071026, 2025). "Identification of high-risk individuals for hypertension based on the rs4309 genotype of the ACE gene may allow for the implementation of targeted lifestyle interventions from an early age, potentially preventing or delaying the onset of hypertension." (PMID 40370871, 2025). "Consequently, the inhibition of ACE activity is a key therapeutic strategy for reducing the risk of hypertension and managing high blood pressure." (PMID 40278278, 2025). "Two polymorphisms on the angiotensinogen gene (rs699 and promoter region variants) and one on the angiotensin I converting enzyme gene (an insertion/deletion polymorphism) have been researched as possible links to the physiological pathways behind HC-induced hypertension." (PMID 41323407, 2025). "By inhibiting ACE activity and preventing the overproduction of angiotensin II, which causes vasoconstriction and elevated blood pressure, taxifolin shows promise as a treatment for hypertension." (PMID 40869372, 2025). "Hypertension and type 2 diabetes are the major metabolic syndromes, often managed using synthetic ACE and DPP-IV inhibitors that may cause adverse effects on health." (PMID 40427700, 2025). "ACE inhibitors are thought to have less blood pressure–lowering effects and increased risk of angioedema in Black individuals with hypertension, and international guidelines preferentially recommend diuretics and calcium channel blockers over ACE inhibitor treatment in these individuals." (PMID 41054850, 2025). "Several SNPs in the ACE gene have been linked to hypertension." (PMID 40370871, 2025). "Given the established critical role of ACE in the pathogenesis of essential hypertension, a significant risk factor for stroke, the findings indicate that individuals carrying the DD genotype may exhibit heightened susceptibility to developing IS." (PMID 41272596, 2025). "Early studies have reported that insertion/deletion (I/D) polymorphism within the ACE locus is responsible for the variability in plasma ACE levels, and the polymorphism of the ACE might be essential in monitoring hypertension." (PMID 38812641, 2024). "As a result, ACE I/D polymorphism may be used as a biomarker for early diagnosis, detection and prevention of hypertension complications." (PMID 39666621, 2024).